CXCR4 (C-X-C motif chemokine receptor 4)
Diseases named in the same sentence as CXCR4 in open-access papers (continued):
Sharing a sentence is not in itself a finding about the gene and the disease.
cancer (continued). "Genes such as NRAS, SPHK2, FOS, CXCR4, PLD1, GNAI2, and PLA2G4F, and their related biological process terms and pathways, such as apoptosis, MAPK signalling pathway, and cancer signalling pathways, may represent potential targets for OA treatment and diagnosis." (PMID 29968759, 2018). "SDF-1 activates two G protein-coupled receptors, CXCR4 and CXCR7; these are expressed in both developing and mature CNSs and participate in multiple physiological and pathological events, e.g., inflammatory response, neurogenesis, angiogenesis, hematopoiesis, cancer metastasis, and HIV infection." (PMID 29123467, 2017). "Another modulator of stromal cells’ derived chemoresistance is the SDF-1α/CXCR4 axis, in which PSCs promote resistance to gemcitabine via paracrine SDF-1α/CXCR4 signaling-induced activation of FAK-AKT and ERK1/2 signaling pathways with subsequent upregulation of IL-6 in cancer cells." (PMID 29144412, 2017). "CXCL12, which encodes the ligand for CXCR4, was not among the chemokine genes we identified whose expression correlated with expression of CXCR4 in the ACC metastases, nor did we find CXCL12 in the cancer cells by IHC." (PMID 29088715, 2017). "NOX-A12, because of its ability to block SDF-1 activity on both of its receptors, CXCR4 and CXCR7, provides additional benefit over a targeted CXCR4 receptor inhibitor because of its dual influence on CXCR7, which affects proliferation, migration, and metastasis of some cancers." (PMID 29299123, 2017). "We can only speculate as to the reason(s) for the increased frequencies of CXCR4+ samples in metastatic versus primary tumors for some (but not all) of the cancers." (PMID 29088715, 2017). "In addition, silencing of CXCR4, a rhodopsin-like G-protein-coupled receptor that selectively binds CXCL12 chemokine, by miR-520h has been shown to successfully block invasion and metastasis of cancer cells." (PMID 28182660, 2017). "Thus, we propose that high CXCR4 on the cell surface, combined with decreased intracellular regulatory GRK3, leads to impaired receptor internalization and more active CXCL12-mediated migration of the cancer cell." (PMID 27049755, 2016). "Therefore, developing agents that can inhibit the action of CXCR4 or CD147, in early and advanced stages of cancer may be effective in preventing and managing metastasis." (PMID 27769052, 2016). "An exception may be the expression of CXCR4, involved in the chemo attraction of cancer cells to CXCL12-rich environments, but not exclusively bone (e.g., brain also)." (PMID 27618899, 2016). "However, if expression or lack of expression of CD49f enriches the CXCR4+ population for functional cancer stem cells needs to be further elucidated." (PMID 26385771, 2016). "Also, binding of gp120 to CXCR4 is involved in HIV-mediated apoptosis of infected and uninfected lymphocytes, neurons, cardiomyocytes, hepatocytes, and different cancer cells." (PMID 26347749, 2015). "However, expression and involvement of CXCR4, CCR7, CCR9, CXCR5 and CX3CR1 in various cancers reported by our laboratory and others suggest that the multi-step process of tumor progression and metastasis is regulated by multiple chemokines and their corresponding receptors." (PMID 25888629, 2015). "As shown in cancer cells, inhibition of EPC function by deguelin may result in part from the suppression of Akt pathways and the hypoxia-induced expressions of VEGF and CXCR4." (PMID 26078334, 2015). "Moreover, the reduction of the expression level of CXCR4 in the metastasized cancer cells is not dependent on the expression level of CXCL12 in the lung tissue around the metastasized cancer cells." (PMID 26083776, 2015). "Thus the definition of mechanisms and downstream mediators of CXCR4/R7 activation by CXCL12, in normal and malignant differentiated cells, their progenitors, and in normal and CSCs, is highly relevant for both cancer biology and perspective therapeutic targeting." (PMID 24904289, 2014).
cancer (continued). "In addition, since CXCR4 and CXCR7 are involved in angiogenesis, targeting this chemokinergic system could improve the poor efficacy of inhibitors of angiogenesis in several cancers including GBM." (PMID 24904289, 2014). "In agreement with the results of the present study, overexpression of CXCR4 in GBMs has been recognized as an attribute of cells with progenitor/stem properties and CXCL12 promotes specifically the proliferation of these cells compared to more differentiated cancer cells." (PMID 24662753, 2014). "Consistent with this hypothesis, the induction of CXCR4 by hypoxia has been reported to depend on both the activation of HIF-1α and the stabilization of the transcript in cancer cells, which is paralleled by an increase in the chemotactic responsiveness to its specific ligand, SDF-1α." (PMID 25396735, 2014). "CXCR4 is a G protein-coupled receptor (GPCR) widely expressed in a variety of cell types including leucocytes, where it promotes migration, recruitment and activation, neurons, where it modulates electrical activity, and various cancers and metastases where it is involved in tumor progression." (PMID 24808825, 2014). "Thus, miRNAs that are necessary for homing to the specific target organ might be activated by CXCR4 upon binding of its ligand, SDF-1 in these cancer cells." (PMID 25536052, 2014). "SW620 cell lines with reduced expression of CXCR3 and/or CXCR4 created using microRNA, CXCR3-, CXCR4-, and CXCR3/ CXCR4 double-knockdowns significantly reduces metastasis to lymph nodes, liver and lungs, and significantly decreases the dissemination of cancer cells to liver and lungs." (PMID 24647809, 2014). "Many different chemokine pathways are known and their role in cancer has been completely and well reviewed by others; therefore, in this review we focus on chemokine axes involved in lymphatic metastasis: the chemokine receptor 7 (CCR7) with its ligands CCL19 and 21 and the CXCR4/CXCR12 axis." (PMID 25254213, 2014). "Since CXCR4- and CXCR7-positive cells were more abundant in the slow-cycling subpopulation in a similar manner to what has been shown with other cancer-stem cell markers, we hypothesized that CXCR4 and/or CXCR7 might regulate cancer stem cell phenotypes." (PMID 23555768, 2013). "We then determined that SDF-1/CXCL12 treatment could further induce EMT in CD133+CXCR4+ cancer cells and enhance their invasive behavior, while this could not be observed in CD133+CXCR4- cancer cells." (PMID 22871210, 2012). "Interestingly, recent data have reported that CXCR4 expression may be influenced by the TGF-β pathway and the phenotype of cancer cells." (PMID 24212636, 2011). "Thus, 15dPGJ2-dependent suppression of CXCR4 seems to be arestraint mechanism that is not operative in a cancer situation." (PMID 18779872, 2008). "CXCR4 stained high or medium in the cytoplasm of 50% borderline tumours and in 33.3% of borderline tumour nuclei, which was not different from the staining frequencies in malignant tumours." (PMID 17245339, 2007). "Nevertheless, the impact of a strong CXCR4 expression on disease progression might depend on the type and location of the primary carcinoma and most likely on other parameters, which have not been defined yet." (PMID 16819541, 2006). "Finally, despite successful pre-clinical studies, the addition of the anti-CXCR4 peptide LY2510924 to cancer therapy did not improve the efficacy of the treatments in phase II studies in lung cancer and renal cell carcinoma, respectively NCT01439568 and NCT01391130." (PMID 39596815, 2024). "Furthermore, CXCR-4 may influence HER2 expression, which promotes cancer dissemination." (PMID 39609700, 2024). "As a growing number of studies have demonstrated that the expression level of CXCR4 in CRC may influence the sensitivity of CRC to chemotherapeutic drugs such as oxaliplatin, the expression of CXCR4 in drug-resistant CRC cell lines for cancer chemotherapy has still been further elucidated." (PMID 36290780, 2022).
cancer (continued). "This may also apply to drug dosing of non-radiolabeled CXCR4-inhibitors used as anti-cancer agents." (PMID 35312939, 2022). "Therefore, blockade of CXCR4/STAT3 pathway could be a promising approach for the efficient sensitizing NSCLC cells to IR, hence being useful for the radiotherapy of this devastating cancer." (PMID 33414415, 2021). "Thus, our novel derivatives encompassing only seven amino acids are more potent in terms of inhibiting CXCR4-downstream signaling and cancer cell migration than the parental peptide, with no toxic effects shown for the shortest JM#21 derivative in the zebrafish toxicity assay." (PMID 34552197, 2021). "With this concern in mind, and considering the fact that CXCR4 is a major receptor of CXCL12, we further tested whether artificial overexpression of ligand CXCL12 in macrophages can prevent the resensitization of cancer cells to docetaxel in the presence of pexidartinib." (PMID 34069563, 2021). "Hence, many but not all types of cancer cells express CXCR4 or CXCR7 in various combinations." (PMID 24770893, 2014). "Therefore, we considered whether the more than 40% of cases without CXCR4 expression might result from the lack of additional mechanisms of control needed for CXCR4 stability in cancer tissue." (PMID 24618817, 2014). "However, CXCR4 interactions alone did not completely explain the pattern of metastasis of cancer." (PMID 20652010, 2010). "In addition, as both Cox-2 and CXCR-4 inhibitions are RhoA-independent, further investigations are required to determine whether the invasion of cancer cells without RhoA activation could be reduced by ZOL." (PMID 12771933, 2003). "We observed that α-SMA negative, PD-1+/CXCR4+ cells in PDAC tissues and PDOs were localized to regions corresponding to ductal and cancer cells." (PMID 35797269, 2022). "Interestingly, we assessed the mRNA levels of the chemokine receptors CCR4 and CXCR4 in GC cells and found that knockdown or overexpression of CPNE8 significantly regulated their expression, implying that CPNE8 may affect the function of CAFs via modulation of chemokine binding to cancer cells." (PMID 35982908, 2022). "Most studies have been focused on myeloid and maturation markers (such as CD10, CD11b, CD15 and CD16, CXCR4, PDL-1) and there is a lack of unbiased analysis of neutrophil heterogeneity in circulation in the setting of cancer." (PMID 34484199, 2021). "Both normal and cancer fibroblasts responded well to SDF-1 stimulation (shown by increase in EMT and invasiveness), whereas the CXCR4 knocked down cells did not significantly respond to the SDF-1." (PMID 33637678, 2021). "In addition, Cells that migrated or invaded through the transwell chamber were also decreased in the CXCR-4-silenced cells upon pDC-CM treatment (P < 0.01), suggesting that CXCR-4 may play an important role in pDC-mediated cancer cell proliferation, migration and invasion." (PMID 33854604, 2021). "The data presented here indicate that inhibitors of TGFβR and CXCR4 do not block CAF- and NF-induced cancer cell migration and invasion, since they did not block Akt phosphorylation but rather increased it." (PMID 32731484, 2020). "IL-17A did not increase CXCR4 (68.19% vs. 64.54%) and ABCG2 (1.96% vs. 1.52%) expression in human L3.6pl cancer cells assessed by flow cytometry." (PMID 32210079, 2020). "A number of antagonists and inhibitors targeting the CXCL12/CXCR4/ACKR3 axis are being developed in cancer indications, mostly in non-brain tumor related cancers and not in combination with radiotherapy." (PMID 30813533, 2019). "On the other hand, the information regarding CXCR4/CXCL12 axis during the development of FMC is almost absent, despite the fact FMC being considered as suitable cancer model." (PMID 30012106, 2018).
cancer (continued). "Notably, CXCR4 antagonists can be used as potential drug sensitizers since treatment-induced CXCL12 pathway activation might be involved in acquired drug-resistance mechanisms through several processes, including induction of cancer cell survival, invasion, and stem cell phenotype." (PMID 27307990, 2016). "CXCR7 regulates CXCL12/CXCR4-mediated cell motility by scavenging CXCL12, both during normal processes (e.g., development) and in the diseased state (e.g., cancer)." (PMID 25884570, 2015). "The expression levels of CCR7, CXCR4 and VEGF-C in the cancer cells were all significantly higher than those in the non-cancerous regions (P<0.05)." (PMID 23761820, 2013). "Similarly, our data on CXCR4 expression, cell viability and proliferation showed no significant alteration after treatment with exendin-4, whereas reduction of cell viability and enhanced apoptosis have been reported for other tumors such as breast and colon cancer cells." (PMID 23990978, 2013). "However, if sorted by CXCR4+, the subpopulation exhibited less efficiency in colony forming ability when compared with the ALDH+ subpopulation (Method S1), suggesting that the ALDH+ subpopulation may contain more cancer stem/progenitor cells of the ZR-75 cell line." (PMID 20027313, 2009). "Ourprevious observations that DIM downregulates CXCR4 and CXCL12 in breast andovarian cancer cells represent a novel mechanism for the chemoprotectiveeffects of this phytochemical." (PMID 19325924, 2009). "However, no reduction in the ratio between mRNA sequences encoding human CXCR4 and GAPDH was observed in any treatment group suggesting that the absence of immobilised CXCL12 in heparin-treated animals did not select for non-CXCR4-expressing variants of the cancer." (PMID 17726466, 2007). "The involvement of HGF in the expression of the ligand/receptor couple CXCL12/CXCR4 has not been studied in EPCs, but we have demonstrated that HGF induces CXCR4 in carcinomas." (PMID 17686146, 2007). "Non-peptide CXCR4 antagonists, including AMD3100, AMD3465 123, 124, AMD11070 125, 126, MSX-122 127, and CTCE-9908 128, have been identified as potential therapeutic for cancer treatment." (PMID 37497001, 2023). "Consequently, specific traits of CXCR4 and FAP cannot be exclusively attributed either to cancer cells or non-malignant immune cells or fibroblasts." (PMID 36672341, 2023). "The mixture of CXCL4 and CXCL12 or the obligate CXCL4•CXCL12 heterodimer inhibited CXCL12-induced migration of MDA-MB-231 breast cancer cells, increased cytoplasmic Ca2+ release and activated downstream signaling of CXCR4 but not CXCR3, highlighting its role in limiting cancer progression." (PMID 37446102, 2023). "Presumably, CXCR4 inhibition by LPA1 may play a role in the lack of correlation between CXCR4 expression and OS in these cancers." (PMID 37749552, 2023). "Mixtures of CXCL4 and CXCL12 or obligate CXCL4•CXCL12 heterodimers inhibited CXCL12-induced migration of breast MDA-MB-231 cancer cells, increased Ca2+ release and activated downstream signaling of CXCR4 but not of CXCR3, highlighting its role in the limitation of cancer progression." (PMID 37446102, 2023). "In addition, N6AMT1 expression had pan-cancer correlations with most of the 45 immunostimulators: in ACC, N6AMT1 expression showed the strongest positive correlation with CXCR4; in UVM, N6AMT1 expression showed the strongest negative correlation with CD276." (PMID 37437243, 2023). "Overall, the study indicates that high levels of CXCR4 intracellular protein but not CXCR4 signaling restricts cellular apoptosis and promotes cell survival via downregulating the DR5 expression and thus renders cancer cells resistant to chemotherapeutic drugs like paclitaxel." (PMID 33966046, 2021). "Targeting of CXCR4 with antibodies or specific inhibitors, most commonly AMD3100, has been intensely investigated; however, AMD3100/Plerixafor/Mozobil has been approved for bone marrow transplantation, but not as anti-cancer treatment." (PMID 32983169, 2020).
cancer (continued). "Along these same lines, CXCL12 that was present in SASP of senescent papillary thyroid carcinoma (PTC) cells played key roles in inducing collective invasion of the cancer cells and in increasing the survival of non-senescent PTC cells, in a CXCR4-dependent manner." (PMID 32582148, 2020). "As a whole, it is therefore evident that, regardless of the exact mechanism leading to CXCL12/CXCR4/ACKR3 over-expression/stimulation in cancer, this axis plays multiple fundamental roles in cancer progression and as such, offers an important potential target for disease treatment." (PMID 30257500, 2018). "These genes will probably be activated at later stages of cancer dissemination, and will be responsible for the adaptation of the cancer cells to the foreign microenvironment, either promoting seeding or colonization (e.g., OPN, and CXCR4) rather than dictating their attraction to a certain organ." (PMID 27618899, 2016). "CXCR4 inhibition may not be sufficient to block the effects of CXCL12, which may also bind to CXCR7 on cancer or stromal cells." (PMID 26062132, 2015). "However, CXCR4 and CXCR7 expression has been reported to have an intracellular location in other cancers such as gallbladder and pancreas without CXCL12 stimulation." (PMID 24497931, 2014). "For modules M3, M4, and M5, although the corresponding GO_BP terms were not directly related to cancer, we found PrCa-relevant genes in these three modules, including BTG2, FOS (also known as c-Fos), and CXCR4 in module M3; ARFGAP3 and CDH1 in module M4; and SMAD3 and MXI1 in module M5." (PMID 25418933, 2014). "Similarly, the CXCR4 and CXCR7 protein expression was absent in polyps and early stages carcinomas but increased between stage II and III, to be highest in the stage IV carcinomas." (PMID 24629239, 2014). "However, even with these limitations, many of the findings discussed have been validated by the fact that the same chemokine systems appear to be involved in mediating bone metastasis regardless of the cancer of origin, in particular CCL2/CCR2, CCL3/CCR1, IL-8/CXCR1, and CXCL12/CXCR4." (PMID 29930538, 2018). "We have also demonstrated for the first time that CXCR4 expression is not altered following cryopreservation in either transduced or untransduced cells and that although there is a reduction in cell migration, there is no reduction in TRAIL transgene expression or cancer cell killing efficacy." (PMID 27260207, 2016). "To evaluate this surprising lack of difference in adhesion selectivity, we next turned our attention to how CXCL12 and receptors CXCR4 and CXCR7 on the vascular endothelia, rather than on cancer cells, may be key determinants in the intravascular adhesion step of metastasis." (PMID 19484126, 2009). "Therefore, CXCR4, PDCD1 and MAP1LC3C may function as non-negligible factors in cancer immunity." (PMID 36173625, 2022). "The results showed that RGS2 and DUSP1 were significantly expressed in the cell population, and three model genes, CXCR4, SLCO2A1, and FNDC1, were not in the cluster, indicating that the two model genes that were significantly expressed could be used as marker genes of cancer." (PMID 36591293, 2022).